TRBJ1-5 (T cell receptor beta joining 1-5)
Description:
J region of the variable domain of T cell receptor (TR) beta chain that participates in the antigen recognition. Alpha-beta T cell receptors are antigen specific receptors which are essential to the immune response and are present on the cell surface of T lymphocytes. Recognize peptide-major histocompatibility (MH) (pMH) complexes that are displayed by antigen presenting cells (APC), a prerequisite for efficient T cell adaptive immunity against pathogens. Binding of alpha-beta TR to pMH complex initiates TR-CD3 clustering on the cell surface and intracellular activation of LCK that phosphorylates the ITAM motifs of CD3G, CD3D, CD3E and CD247 enabling the recruitment of ZAP70. In turn ZAP70 phosphorylates LAT, which recruits numerous signaling molecules to form the LAT signalosome. The LAT signalosome propagates signal branching to three major signaling pathways, the calcium, the mitogen-activated protein kinase (MAPK) kinase and the nuclear factor NF-kappa-B (NF-kB) pathways, leading to the mobilization of transcription factors that are critical for gene expression and essential for T cell growth and differentiation. The T cell repertoire is generated in the thymus, by V-(D)-J rearrangement. This repertoire is then shaped by intrathymic selection events to generate a peripheral T cell pool of self-MH restricted, non-autoaggressive T cells. Post-thymic interaction of alpha-beta TR with the pMH complexes shapes TR structural and functional avidity.
Synonyms: TRBJ15; TCRBJ1S5
Gene: T-cell receptor joining (J) gene on chromosome 7 (142,788,498 to 142,788,547, forward strand). Ensembl gene ENSG00000282173.
Subcellular location: Cell membrane
Gene Ontology:
Cellular component: plasma membrane